KIT (KIT proto-oncogene, receptor tyrosine kinase)
Diseases named in the same sentence as KIT in open-access papers (continued):
Sharing a sentence is not in itself a finding about the gene and the disease.
breast carcinoma (148 papers, 2004 to 2025). "To date, no clear association exists between BRCA1/2 mutations and GIST, with only rare reports available, including a patient harboring simultaneous BRCA2 and KIT germline mutations manifesting as breast cancer and multiple GISTs, respectively." (PMID 39199677, 2024). "Our analysis indicates that KIT mutations correlate with elevated serum levels of galectin-9 in patients with breast cancer." (PMID 38927753, 2024). "This study found a significant correlation between a cancer-critical KIT mutation and higher serum galectin-9 levels in breast cancer patients, similar to other studies." (PMID 38927753, 2024). "It allows for addressing the role of KIT mutations in breast cancer and identifying genetic and environmental modifiers of disease progression." (PMID 36396684, 2022). "It is especially expected to help shedding light on the yet still unclear role of KIT mutations and KIT signaling in mammary carcinoma." (PMID 36396684, 2022). "Further, certain types of malignant breast cancer are associated with KIT overexpression, but the relevance of KIT mutations for mammary carcinoma development is unclear, since activating KIT mutations are rarely found in this context." (PMID 36396684, 2022). "Mutations in the KIT proto-oncogene, which codes for the c-Kit protein, a receptor tyrosine kinase, correlated with higher levels of galectins -1, -3, -8, and -9 in breast cancer patients and galectin-1 in non-small cell lung cancer patients." (PMID 35681762, 2022). "Meanwhile an association of strong KIT expression with high-grade breast carcinomas of the basal-like subtype has been shown." (PMID 36396684, 2022). "DNA methylation-mediated loss of KIT expression during malignant transformation was also reported in breast cancer." (PMID 34639089, 2021). "Loss of c-KIT expression in breast cancer is related to malignant transformation of breast epithelium and performed by KIT gene promoter DNA hypermethylation." (PMID 33282730, 2020). "Immunolocalization of c-KIT is reported in normal breast epithelial cells with loss of c-KIT in low-grade breast cancers." (PMID 31248446, 2019). "We have previously demonstrated that Brca1 mutation-associated breast cancers originate from luminal ER− progenitors and that c-KIT and LYN are expressed in mouse Brca1 mammary tumors." (PMID 30590041, 2018). "c-KIT positive cells can be the cell of origin in some ER-ve /HER2-ve breast cancers, and c-KIT expression is particularly associated with the triple negative subtype." (PMID 29796188, 2018). "The KIT or CD117 gene codes for a receptor tyrosine kinase that is frequently overexpressed or mutated in breast cancer metastatic to brain." (PMID 30135398, 2018). "In addition, metastatic breast cancer samples were more likely to have a KIT or PIK3CA mutation compared to primary breast cancer samples." (PMID 38927753, 2024). "Less clear is the role of KIT mutations in the context of breast cancer." (PMID 36396684, 2022). "The signal-transduction pathways involving vascular endothelial growth factor receptor (VEGFR), platelet-derived growth factor receptor (PDGFR), stem-cell factor receptor (KIT), and colony stimulating factor-1 receptor (CSF-1R) have been implicated in breast cancer pathogenesis." (PMID 24914410, 2014). "Interestingly, the tyrosine kinase KIT was reported to be overexpressed in basal breast cancers and BRCA1-associated basal cancers, suggesting that it may serve as a useful prognostic marker or therapeutic target." (PMID 20346151, 2010). "We prove that KITLG increases programmed cell death in breast cancer cells and augments apoptosis by stimulating the transcription of c-KIT genes." (PMID 38213737, 2024). "It is a downstream target of c-KIT signalling in luminal epithelial stem/progenitor cells of the mammary gland and also expressed in breast cancers, particularly TNBC." (PMID 38149669, 2024).
breast carcinoma (continued). "As a result of our protein network investigation, the proto-oncogene c-KIT (KIT) protein was identified as a potent radioresistant breast cancer target." (PMID 37888480, 2023). "It is important to note that in this particular breast cancer tissue, the c-KIT stain on mast cells should be interpreted with caution as it also stains normal breast epithelium." (PMID 37928785, 2023). "For tumors like breast cancer, where KIT expression strongly correlates with immune infiltration signatures, KIT is most probably mainly expressed by the infiltrating immune cells." (PMID 35887076, 2022). "In human breast cancer KIT expression is downregulated during epithelial transformation by KIT promoter hypermethylation." (PMID 36396684, 2022). "Histological analysis of tumors derived from 14 different mice including three with more than one tumor revealed these neoplasms to be KIT-expressing mammary carcinomas." (PMID 36396684, 2022). "Normal breast ducts and acini, but not myoepithelial and stromal cells, show some expression of c-KIT, which has been reported to be lost in most breast cancers." (PMID 35490363, 2022). "The increased expression of KIT enhances the proliferation and metastasis of breast cancer, rectal cancer, and other cancer cells." (PMID 34582363, 2021). "KIT amp, EGFR amp, MET amp and ALK mutation in lung cancer, and CCNE1 amp in breast cancer were curated as resistant information only in the QCII." (PMID 31383922, 2019). "Imatinib mesylate (Gleevec®) was previously evaluated in advanced/metastatic breast cancer expressing c-KIT or PDGFR." (PMID 30634402, 2019). "ErbB-2 class receptor binding was enriched in basal cells (q = 0.004), and numerous pathways critical to cell differentiation, survival and breast cancer were enriched in luminal including c-KIT, NOTCH, and GH receptor signaling." (PMID 29921600, 2018). "A high level of proto-oncogene receptor tyrosine kinase, KIT, expression is a well-known driver of proliferation of breast cancer cells." (PMID 29299133, 2017). "In canine mammary tumours, a positive correlation between c-KIT and Ki67 expression has been demonstrated." (PMID 29207991, 2017). "c-KIT expression has been studied in different canine tumours, including mast cell tumours, mammary tumours, seminomas, liposarcomas and gastrointestinal stromal tumours." (PMID 29207991, 2017). "In summary, we demonstrate that metastatic breast cancer patients have an increased frequency of circulating KIT+CD11b+ cells, M2-polarized CD11b+ cells and elevated levels of the M2 cytokine IL-10 and CCL20." (PMID 26840567, 2016). "Results obtained from The Cancer Genome Atlas Network for both colorectal and breast cancer showed the co-existence of mutations in these genes, although in low proportions (4.93% for PIK3CA and KIT and 1.23% for KIT and RET)." (PMID 26968814, 2016). "We have previously reported that circulating KIT+CD11b+ cells promote metastasis in the 4T1 murine model of breast cancer relapse after radiotherapy." (PMID 26840567, 2016). "In this study, gene copy number and protein expression were evaluated for three RTKs as potential breast cancer drug targets: c-KIT, vascular endothelial growth factor receptor-2 (VEGFR2) and PDGFRα." (PMID 25025175, 2014). "In conclusion, we have found that the proteins c-KIT, VEGFR2 and PDGFRα, encoded by genes at 4q12, are associated to the St Gallen breast cancer subgroup TNBC." (PMID 25025175, 2014). "Other signaling proteins included KIT, a transmembrane receptor tyrosine kinase, which was recently proposed as a poor prognostic marker in basal-like breast cancer." (PMID 25183703, 2014). "KIT is co-expressed with EGFR and is associated with BRCA1-mutation carriers and in sporadic basal-like breast cancer." (PMID 23593654, 2013).
breast carcinoma (continued). "A more recent report, however, examining a large series of breast carcinomas (n = 924), concluded that KIT was expressed in 15% of breast cancer patients and was a prognostic indicator of poor clinical outcome." (PMID 22897944, 2012). "KIT overexpression has also been reported to occur more frequently in ductal carcinomas compared with other breast cancer histologies." (PMID 22897944, 2012). "For instance, KIT overexpression in GISTs is driven by activating KIT mutations, whereas HER2 overexpression in breast cancer is driven by HER2 gene amplification." (PMID 19707201, 2009). "In GISTs (KIT and PDGFRA mutations), breast carcinoma (HER-2 amplification) and lung cancer (EGFR mutation), targeted therapy has yielded best results in cases with activating mutation or amplification of the respective gene." (PMID 15583695, 2004). "Conversely, certain studies have indicated that the absence of KIT is detected while breast cancer is progressing and is associated with the occurrence of malignancy." (PMID 38189813, 2024). "Furthermore, the community cohesion scores successfully discover the known breast cancer subtypes and we suggest new targeted therapy targets for triple negative breast cancer (e.g. KIT and GABRP)." (PMID 38622359, 2024). "Another type of breast cancer in which the expression of c-KIT is frequently seen is adenoid cystic carcinoma (ACC) of the breast that, although relatively clinically indolent, can be confounded with infiltrating duct carcinomas (particularly with tubular and cribriform carcinomas of the breast)." (PMID 35490363, 2022). "In addition, high KIT mRNA expression in basal-like breast cancer is correlated with shorter overall survival." (PMID 34718356, 2022). "Galectins -1, -3, -8, and -9 were found to be at higher levels in sera of breast cancer patients with a mutation in the KIT gene than other cancer patients without the mutation." (PMID 35681762, 2022). "These seven proteins—(CRMP2, C-RAF, CYP17, c-KIT+ VEGFR, and HDAC9)were considered in this in silico study owing to their association with several cancers: breast cancer, liver cancer, prostate cancer, kidney cancer (for both C-KIT and VEGFR), and stomach cancer." (PMID 36354673, 2022). "Moreover, increased expression of KIT was reported to be more common in basal-like breast cancer and was correlated with poor patient survival." (PMID 34718356, 2022). "An interesting phenotype we observe in our mice, which to our knowledge has not been described for any other KIT-activating mutation model, is the development of mammary tumors in female mice aged 8 months and older." (PMID 36396684, 2022). "Interestingly, we found that SDH-deficient GISTs showed TIS scores closer to glioblastoma multiforme and kidney renal papillary cell carcinoma, while KIT-mutant GISTs placed near to breast cancer and pancreatic adenocarcinoma." (PMID 33806389, 2021). "The receptor tyrosine kinase KIT (c-Kit) has previously been identified as a defining marker of mammary epithelial progenitor cells and of the cells of origin of BRCA1-mutation breast cancer, luminal ER− cells." (PMID 32793804, 2020). "Another example is c-KIT/CD117, the expression of which has been shown to associate with neutrophil maturity in naïve mice, mice undergoing candida-induced emergency granulopoiesis, and a mouse model of breast cancer." (PMID 31474989, 2019). "In dogs with mammary tumors, c-KIT exhibits a controversial role in tumorigenesis." (PMID 30634402, 2019). "It is possible that this ER-ve SCLC plasticity is a feature of subsets of cancer cells, accounting for the observations that c-KIT knockdown effectively eliminates the 3D culture potential of primary mammary cells, whereas therapies targeting c-KIT in breast cancer patients have had limited success." (PMID 29796188, 2018).
breast carcinoma (continued). "Notably, six of the top 10 IgSF genes in the PPI network were well-known breast cancer driver genes, including KIT, whose high expression occurs infrequently in breast cancer." (PMID 27911271, 2017). "At present, KIT mutations are without clinical implications in the current therapeutical approach to colorectal and breast cancer." (PMID 26968814, 2016). "KIT is a cytokine cell-surface receptor that binds to stem cell factor and has been indicated as an emerging therapeutic target for breast cancer therefore may itself be effective at treating this disease." (PMID 23593654, 2013). "Given the heterogeneity of breast cancer overall and of sub-types such as TNBC in particular, a prospective biomarker-driven study would be required to definitely assess the role of KIT and the utility of sKIT in determining the outcomes of breast cancer patients treated with KIT inhibitors." (PMID 22897944, 2012). "The associations between changes in sKIT and clinical outcome described in this study suggest that better characterization of breast cancer subtypes expressing KIT and elucidation of its role in control of tumor growth may be worthwhile." (PMID 22897944, 2012). "Activating KIT mutations have not so far been reported in breast cancer, although research to date has utilized patient series of limited size." (PMID 22897944, 2012). "In the context of breast cancer, genes within the conserved signatures, such as those that characterize the more purified luminal progenitor subset (for example, KIT, CYP24A1, ELF5), have the potential to provide novel prognostic markers or therapeutic targets in breast cancer." (PMID 20346151, 2010). "However, the molecular mechanisms by which c-KIT regulates breast cancer cell proliferation remain unclear." (PMID 38690279, 2024). "We then compared the distribution of POU2F3-positive cells and cells expressing ER, CK5 (a basal marker), and oncogenes often expressed in tuft cell-like cancers (BCL2 and KIT) to ask whether the POU2F3-positive cells had a phenotype similar to tuft cell-like breast cancers." (PMID 37179317, 2023). "The genes sharing these GO terms have been previously shown to be involved in breast cancer prognostic process (e.g., CXCR6, KIT, RUNX3) and also immune cell regulation (e.g., CD8B, DAPP1, LY75)." (PMID 33919884, 2021). "The SRC-family kinase LYN is highly expressed in triple-negative/basal-like breast cancer (TNBC) and in the cell of origin of these tumors, c-KIT-positive luminal progenitors." (PMID 30590041, 2018). "We previously observed elevated levels of VEGFR1+CD11b+, KIT+CD11b+ and JAM1+CD11b+ (unpublished data) in murine models of breast cancer and TIE2+CD11b+ cells in mBC cancer patients." (PMID 26840567, 2016). "Breast cancer patients had elevated frequencies of CEC, CEP, TIE2+CD11b+ and KIT+CD11b+ cell subsets." (PMID 26840567, 2016). "A previous study has shown that increased gene copy number of c-KIT and VEGFR2 in primary breast cancer is related to an aggressive phenotype and impaired prognosis." (PMID 25025175, 2014). "High expression of c-KIT and VEGFR2 has previously been correlated to basal-like breast cancer (BLBC) and TNBC." (PMID 25025175, 2014). "A number of cell surface markers have been used to sort for breast cancer cells with tumor-initiating capacity, including CD44, CD133, ALDH, CD90, and CD117 (KIT)." (PMID 22233382, 2012). "Expression of KIT, a member of the PDGFR subfamily, has also been detected in breast cancer cells with a prevalence of between 1% and 25%." (PMID 22897944, 2012).
breast carcinoma (continued). "In addition to these clearly malignant clusters, we identified a population of luminal progenitor-like cells (LP; KIT, ELF5), which are considered the presumptive cells of origin for breast cancer and are indicative of cancer stemness." (PMID 40858992, 2025). "The results showed that the expression of both CSF1 and KIT was significantly downregulated in breast cancer tissues compared to non-tumor samples." (PMID 37445965, 2023). "The expression levels of the CSF1 and KIT genes were compared between breast cancer and adjacent non-tumor tissues from patients, using original published data available in the GEPIA database." (PMID 37445965, 2023). "MCF7 (a breast cancer cell line, not dependent on KIT pathway) and MRC5 (normal fibroblast cell line) were used as control cell lines." (PMID 34324512, 2021). "The cells of origin of BRCA1-associated mammary tumours, the mammary luminal epithelial estrogen receptor (ESR1)-negative stem/progenitor population, express the c-KIT (or KIT) receptor tyrosine kinase at high levels, as well as its downstream pathway member, the SRC-family kinase LYN." (PMID 38149669, 2024). "Our sample population did not contain a breast cancer sample with a brain metastasis and wild-type KIT and therefore, no ratio could be calculated for the group." (PMID 35681762, 2022). "Given that SRp55 is commonly mutated in breast and colorectal cancers, and influences the alternative splicing patterns of several tumor-associated genes like KIT, CD44, and FGFR1, it is not surprising that SRp55 depletion decreased the invasion of breast cancer cells." (PMID 32756405, 2020). "However, although in the K14-Cre;Cdh1F/F;Trp53F/F, and 4T1 mouse mammary tumor models, neutrophil c-KIT expression is enriched on immature neutrophils, it fails to completely correlate with maturation status." (PMID 31474989, 2019). "Whereas studies in breast cancer cells have indicated that HIF-1α crucially regulates expression of stem cell factor (SCF), a c-KIT ligand, results on small-cell lung cancer cells indicated that activated SCF-c-KIT stimulated HIF-1α-mediated VEGF expression via PI3K/Akt activation." (PMID 26760782, 2016). "Other studies also describe a relationship between the expression of c-KIT and CK17 and the basal-like subtype of breast cancer, but these markers are not that frequently positive as CK5/6." (PMID 17088909, 2006). "The aim of this study was to analyze protein expression and gene copy number for c-KIT, VEGFR2 and PDGFRα in order to elucidate if there is a correlation between the copy number of these genes, their protein expression, and the prognosis of breast cancer in the TNBC subgroup compared to non-TNBC." (PMID 25025175, 2014).